ADAMTS1 (ADAM metallopeptidase with thrombospondin type 1 motif 1)
Diseases named in the same sentence as ADAMTS1 in open-access papers (continued):
Sharing a sentence is not in itself a finding about the gene and the disease.
cancer (continued). "Our data suggest a positive correlation between ADAMTS-4 and -5 expression and cancer progression, in contrast with the anti-angiogenic members of the family, ADAMTS-1 and -20, which were found to be down-regulated." (PMID 25786261, 2015). "It has been shown that serglycin expression is markedly upregulated in cancer-activated fibroblasts among other inflammatory mediators and a disintegrin and metalloproteinase with thrombospondin motifs 1 (ADAMTS-1) promoting cancer cell invasion." (PMID 26581653, 2015). "Of the 19 proteases belonging to this family, considerable attention has been paid to the role of ADAMTS1 in cancer pathophysiology." (PMID 25285958, 2014). "We also found a relationship between ADAMTS-1 and the activity of invadopodia, membrane protrusions related to the initial steps of cancer invasion." (PMID 23289900, 2013). "The mechanism, which prevents EZH2 from binding to ADAMTS1 promoter in cancer cell-precocultured NAFs, is currently under investigation." (PMID 22514714, 2012). "Blocking of ADAMTS1 with the corresponding antibodies greatly impaired 199C's cancer invasion promotion function on both MDA-MB-468 and MDA-MB-231 cells in an ADAMTS1 Ab dose-dependent manner." (PMID 22514714, 2012). "Taken together, these experiments strongly indicate that fibroblasts promote cancer cell invasion through secreting ADAMTS1." (PMID 22514714, 2012). "Subsequently we examined the cancer invasion promotion function of ADAMTS1 secreted from fibroblasts." (PMID 22514714, 2012). "Reports of differential expression of ADAMTS1 in several cancer types strongly suggest a role for ADAMTS1 in cancer." (PMID 24213506, 2012). "Given that CAF-secreted ADAMTS1 exhibits promotion ability for cancer invasion, it's highly possible that ADAMTS1 secreted from CAFs contributes more than that from cancer cells to facilitate cancer invasion." (PMID 22514714, 2012). "ADAMTS1 expression in cancer cells is capable of increasing tumor growth and cancer cell metastasis." (PMID 22514714, 2012). "The potential implication of ADAMTS-1 in regulation of cancer-related angiogenesis should be studied more in depth especially regarding factors stimulating or inhibiting this protease." (PMID 16495931, 2006). "ADAMTS1 mediates cancer metastasis through degrading ECM components." (PMID 40878842, 2025). "Also, a previous study demonstrated that the knockout of ADAMTS1 inhibits vasculogenic mimicry (VM) formation, which is considered to promote cancer progression." (PMID 40878842, 2025). "In in vivo experiments, EGFR-KD markedly reversed ADAMTS1-induced dissemination of cancer cells." (PMID 39333870, 2024). "Moreover, ADAMTS14 and 18 are upregulated in most cancers, while ADAMTS1, 8, 9, 10 and 15 are downregulated across the board." (PMID 38948119, 2024). "So far, the functions of ADAMTS1 in cancer progression remain diverse across various cancer types." (PMID 39333870, 2024). "Other studies have also suggested that ADAMTS1 plays both protumorigenic and antitumorigenic roles in cancer, depending on whether its expression is dysregulated in tumor cells or the surrounding stroma." (PMID 36813235, 2023). "Promoter hypermethylation of ADAMTS1 gene has a role in angiogenesis and cancer metastasis." (PMID 36803844, 2023). "Just like in any other carcinoma, Ca Pancreas cells mobilize themselves through the surrounding stroma via proteases and, during our review, it was noted that ADAMTS1, ADAMTS 8, ADAMTS 9, and ADAMTS 18 were highly expressed by them and associated with early nodal, as well as distant metastasis." (PMID 37623681, 2023). "The role of ADAMTS1 in oncology has been investigated in various cancers in the past decade." (PMID 35625488, 2022). "We found that ADAMTS1 could be exploited as a prognostic predictor and therapeutic target due to its effect on the mesenchymal phenotypic transition and cancer immune microenvironment." (PMID 35625488, 2022).
cancer (continued). "In addition, matrix metalloproteinase (MMP), ADAMTS1 and Snail are factors associated with cancer migration and invasion; thus, we analyzed MMP-2, MMP-9, ADAMTS1, and Snail expressions in EGFL6 siRNA treated HCT116 and HT29." (PMID 33726836, 2021). "Thus, the methylation of ADAMTS1 proved to be positive in 87.5% of patients with stage I cancers, 77.8% of patients with stage IIA, 90% of patients with stage IIB, and 100% of patients with stage III/IV PC." (PMID 33114412, 2020). "This upregulation could be due to the fact that Caco-2 and HT29-MTX cells are cancer cell lines and the proteolytic activity of ADAMTS1 has been related to local tissue invasion in cancer." (PMID 30755679, 2019). "Similarly, ADAMTS-1 is capable of stimulating cell invasion during cancer metastasis by digesting ECM32–34." (PMID 28955046, 2017). "Interestingly, three of these genes, MMP19, ADAMTS1, and MMP13, have been previously implicated in the regulation of angiogenesis, extra-cellular matrix, cell adhesion, and cancer progression." (PMID 27227769, 2016). "That ADAMTSs can have both pro- and anti-tumorigenic functions, depending on the cancer and its context, is best illustrated by ADAMTS1, which is down-regulated in breast, primary head and neck carcinomas, and epigenetically silenced in around 85 % of colorectal cancer cell lines." (PMID 26025392, 2015). "Thus, it's very likely that the change in H3K27 trimethylation, rather than DNA methylation, governs this epigenetic memory, which contributes to the sustained expression of ADAMTS1 in cancer cell-precocultured NAFs." (PMID 22514714, 2012). "Indeed, a previous study has revealed a role of cancer cell-expressed ADAMTS1 in metastasis with a mechanism involving activation of epidermal growth factor receptor and ErbB-2 and shedding of amphiregulin and heparin-bound epidermal growth factor precursors." (PMID 22514714, 2012). "Interestingly, we found that both the mRNA and protein levels of ADAMTS1 in CAFs are much higher than those in cancer cells such as MDA-MB-468 and MDA-MB-231." (PMID 22514714, 2012). "Since ADAMTSs are ECM metalloproteinases, cleavages of their substrates also might promote cancer cell invasion and metastasis as in the case of ADAMTS1." (PMID 24213506, 2012). "ADAMTS1 was chosen for this study due to its reported essential role in cancer metastasis." (PMID 22514714, 2012). "ADAMTS1 has been shown to play a role in cancer cell metastasis." (PMID 20840749, 2010). "We investigated whether PGF2α via the FP receptor could promote cell invasion of the ECM, a critical step in cancer cell metastases, via the induction of ADAMTS1." (PMID 20840749, 2010). "Thus, TIMP3 and ADAMTS1 are genes classically correlated to invasion and the metastatic process, the main cancer attributes responsible for death." (PMID 19055846, 2008). "The pro-tumoural effects of MCP-1, proliferin, TIMP-1 and soluble ICAM-1 whilst the anti-cancer effects of IGFBP-2, endostatin and ADAMTS-1 have been published and suggest that this secretome signature may well provide a combination of effects on cancer growth." (PMID 33730293, 2021). "Normal prostate stromal cells isolated from human tissue specimens have been shown to induce the up-regulation of several genes encoding secreted proteins including ADAM metallopeptidase with thrombospondin (TSP) type I motif, 1 (ADAMTS1) whereas CD90+ cancer associated stromal fibroblasts did not." (PMID 24260246, 2013). "Our present results suggested that L1CAM is another downstream effector of ADAMTS1 that regulates EGFR activity and cancer progression." (PMID 38263290, 2024). "In the clinic, the poor prognostic effects of ADAMTS1, L1CAM, and EGFR were observed only in HNSCC among 33 different cancer types suggesting that the ADAMTS1-L1CAM-EGFR axis plays a specific role in regulating OSCC progression." (PMID 38263290, 2024).
cancer (continued). "Other DSG3-associated cancer-related genes include upregulated OLFM4 (antiapoptotic factor), downregulated ADAMTS1 (antiangiogenic activity), downregulated KRT84 (cancer suppressor in oral SCC) and FLNC." (PMID 38067138, 2023). "Expression of several genes known to be involved in cancer progression were identified by this method, including HMGA2, FHL1, SLC2A3, ADAMTS1, UPP1, and TGM2." (PMID 32054828, 2020). "We now show that a two-gene methylation panel (ADAMTS1 and/or BNC1) demonstrated significant improvement in the detection rate, showing an even higher rate of positivity in stage I and stage II cancers (100% and 94.4%, respectively)." (PMID 30953539, 2019). "Overall methylation of either gene (ADAMTS1 and/or BNC1) was observed in 97.4% of cancer patients (38/39) compared to 8.4% of control patients (8/95)." (PMID 30953539, 2019). "ADAMTS-1 was mostly expressed by stroma cells, in contrast to ADAMTS-20 which was expressed by cancer cells." (PMID 25786261, 2015). "The different expression levels of ADAMTS-1 and-20 in CRC, despite their individual differences, further differentiate their implication in cancer, as compared to ADAMTS-4 and -5." (PMID 25786261, 2015). "ERG triggered the migratory potential of cancer cells by the overexpression of CXCR4 and ADAM metallopeptidase with a thrombospondin type 1 motif, 1 (ADAMTS1) as ChIP assay demonstrated direct binding of ERG to the promoter region for both CXCR4 and ADAMTS1." (PMID 24739220, 2014). "Future investigations are needed to determine the precise mechanisms by which ADAMTS-1 and VEGF regulate the invasiveness of cancer cells." (PMID 23289900, 2013). "To further confirm the specificity of ADAMTS1 in the invasion promotion function, we also knocked down ADAMTS1 expression in CAF 199C using a shRNA lentiviral system and found that ADAMTS1 depletion significantly reduced CAF 199C-mediated cancer invasion." (PMID 22514714, 2012). "These genes in addition to ADAMTS1 were also hypermethylated in comparable frequencies among MSS and MSI carcinomas." (PMID 19117505, 2008). "Genes with cancer inhibitory activities that were also upregulated include SERPINE 2 (serine/cysteine protease inhibitor 2, 7 ± 1-fold increase) and ADAMTS 1 (a disintegrin-like and metalloprotease with thrombospondin type 1 motif, 7 ± 2-fold increase)." (PMID 15972109, 2005). "ADAMTS1 as an ECM-degrading protease that was shown to indirectly induce its prometastatic effects by cleaving its substrates such as proteoglycans in the ECM and liberating cancer cells from structural barriers." (PMID 38263290, 2024). "Importantly, hypoxia is an important factor that induces cancer metastasis, following 7 weeks, hypoxia increased expression of MMP2 and ADAMTS1." (PMID 30755679, 2019). "ADAMTS1 and ADAMTS9 have been found to be epigenetically silenced in diverse malignant tumors." (PMID 30081852, 2018). "Taking together these data, it could be said that although ADAMTS-1 and -20 are both generally down-regulated in CRC, their low expression came from stroma or stroma-induced cancer cells, respectively, where they were present as fragments." (PMID 25786261, 2015). "In this cluster, ADAMTS1 and GART are known cancer biomarkers in ALL." (PMID 21044360, 2010). "Therefore, the fine balance between ADAMTS1 and ADAMTS15 could represent a mechanism to precisely tune the levels of syndecan-4 at the plasma membrane, to drive cancer cell migration." (PMID 38948119, 2024). "Importantly, the lack of EZH2 binding and the H3K27 methylation on the ADAMTS1 promoter were sustained in cancer cell-precocultured NAFs after removal of cancer cells." (PMID 22514714, 2012). "Moreover, ADAMTS-1 expression has been found in alveolar bone and periodontal ligament, ECM remodeling, morphogenesis/embryogenesis, follicular development and ovulation, cyclic endometrial remodeling, angiogenesis, as well as in the development of cancer, thrombotic and inflammatory conditions." (PMID 33676487, 2021).
cancer (continued). "However, carcinoma samples with MMP-11 positive MICs showed a more important increase in the mRNA level of 19 factors: IL-1, −5, −6, −8, −17 and −18, ADAM-8, −10, −15, and −23, ADAMTS-1, −2, and −15, IFNβ, MMP-1, as well as mediators related to inflammation (CCL-3, IRAK-4, MyD88 and NFκB)." (PMID 23145063, 2012). "The promoters of ADAMTS1, MAL, and MGMT were frequently methylated in benign samples as well as in malignant tumors, independent of microsatellite instability." (PMID 19117505, 2008). "Hypermethylation of genes such as ADAMTS1 and MAL are also suitable biomarkers for early detection, as they are infrequently methylated in normal mucosa taken from individuals without cancer (0% and 5%, respectively), but highly methylated in malignant lesions (71% and 82%, respectively)." (PMID 19117505, 2008).
adenocarcinoma (2 papers, 2006 to 2013). A common cancer characterized by the presence of malignant glandular cells. "ADAMTS-1 (a disintegrin and metalloproteinase with thrombospondin motifs) was the first described isoform in this family, and this identification was based on its elevated expression in cachexia-inducing adenocarcinomas in mice." (PMID 23289900, 2013).
cardiovascular disease (2 papers, 2020 to 2025). "The core features of PAH: perivascular inflammation, severe ECM dysregulation, and the resulting pulmonary arterial stiffness, all belong to pathological processes in which ADAMTS1 has been demonstrated to be deeply involved in other cardiovascular diseases." (PMID 41440846, 2025). "A number of studies have also investigated the potential role of ADAMTS-1, -4 and -5 in cardiovascular disease." (PMID 33352066, 2020). "In summary, ADAMTS1 is a classic “double-edged molecule” in cardiovascular disease, with its ultimate function, whether protective or pathological, highly dependent on the environment." (PMID 41440846, 2025).
hematologic malignancies (1 paper, 2020). "ADAMTS1, one of the extracellular degrading enzymes, plays an essential role in aberrant tissue remodeling of the peritumoral environment but its role in hematologic malignancies is not known." (PMID 32629802, 2020).
neurodegenerative disease (1 paper, 2024). A disorder of the central nervous system characterized by gradual and progressive loss of neural tissue and neurologic function. "Hsa-miR-548 k targets genes that are involved in Aβ uptake and clearance by microglia, such as IDOL, or regulation of inflammatory processes, such as ADAMTS1, both linked to neurodegenerative diseases." (PMID 38229129, 2024).
ADAMTS1 also shares sentences with these, for which no sentence is quoted: acute myocardial infarction (4 papers); asthma (2); bone metastasis (2); diabetes (2); kidney cancer (2); mesothelioma (2); Obesity (2); pulmonary hypertension (2); radicular cyst (2); abdominal aortic aneurysm (1); adrenocortical carcinoma (1); aneurysmal disease (1); Anorexia (1); Anxiety (1); benign prostatic hyperplasia (1); bipolar disorder (1); cerebral malaria (1); cervical carcinoma (1); chondrodysplasia (1); Cirrhosis (1); colorectal adenoma (1); connective tissue disorder (1); coronary atherosclerosis (1); dementia (1); endometrial polyp (1); epilepsy (1); genetic disorders (1); head and neck tumor (1); infarction (1); infection (1).
A further 24 diseases each share a sentence with ADAMTS1 in 1 paper.